CCL2 (C-C motif chemokine ligand 2)
Diseases named in the same sentence as CCL2 in open-access papers (continued):
Sharing a sentence is not in itself a finding about the gene and the disease.
Stroke (continued). "We observed increased stem cell engraftment by CCL2-overexpressing hUC-MSCs as compared with naïve hUC-MSCs and found that elevated CCR2 levels in the peri-infarction area during acute phase of stroke promoted the migration of CCL2-overexpressing hUC-MSCs into the brain." (PMID 33096826, 2020). "Furthermore, in our study, the sustained increase in CCL2 levels in the brain following transplantation of CCL2-overexpressing hUC-MSCs might induce further increases in the migration of monocytes and macrophages, which are involved in neurological recovery after stroke." (PMID 33096826, 2020). "Increased levels of CCL5, CCL2, CCL3, and CXCL12 found in the early phase of endothelin-1 induced stroke model were not the cause of neurodegeneration." (PMID 27635404, 2016). "Furthermore, it has been shown that CCL2 activates microglia by triggering the release of IL-1β and TNF-α as well as by up-regulating their CCR2 expression level in a mouse model of stroke." (PMID 27930721, 2016). "Whereas all investigated chemokines were found to be unchanged in their acute response at 12 h after stroke (TREM2-KO vs. WT), the increased expression of CCL3 and CCL2 was attenuated in TREM2-KO mice at 7 d after stroke (CCL3: to 12% ±1.3, CCL2: to 37% ±6.5, p≤0.05, n = 5/6 each)." (PMID 23301011, 2013). "Indeed, TNFα, IL-1α, IL-1β, CCL2, CCL3 and CX3CR1 transcript expression differed in the ischemic cerebral tissue of TREM2-KO mice compared to littermate controls at day 7 after stroke." (PMID 23301011, 2013). "However, the prognostic value of other chemokines, such as CCL2, CCL5, or CXCL8, which have been studied in animal stroke models, remains unclear." (PMID 38861234, 2025). "Notably, at earlier time points within 24 h post-stroke, microglial M1 polarization is significantly enhanced, accompanied by elevated levels of pro-inflammatory cytokines like TNF-α, IL-1β, IL-6, and chemokines C-C motif chemokine ligand 2/3 (CCL2/3)." (PMID 39633709, 2024). "Interestingly, Cxcl1 expression was persistently reduced 72 h after stroke in Il1−/− mice, whereas Cxcl2 and Ccl2 already tended to normalize to WT levels." (PMID 35384588, 2022). "Chemokines including macrophage inflammatory protein-1α (MIP-1α or CCL3), monocyte chemotactic protein-1 (MCP-1 or CCL2) and regulated upon activation, normal T-cell expressed, and secreted (RANTES or CCL5) have shown to be released during different models of stroke." (PMID 34572077, 2021). "However, recent studies show that CCL2/CCR2 interaction positively affects functional recovery from stroke, and other studies confirm that CCL2 promotes the homing of CCR2-expressing stem cells from the bone marrow to the damaged brain, which contributes to brain repair following stroke." (PMID 33096826, 2020). "Similarly, it would explain the finding that rtPA failed to decrease stroke-induced increases of IL-6 and CCL2 protein levels in ischemic ColXV KO mice." (PMID 28079884, 2017). "This is consistent with a CCL2 gradient from ischemic to non-ischemic brain tissue to recruit microglial cells and with a pro-inflammatory role of CCL2 in the clinical situation of stroke that might contribute to secondary neuronal cell death." (PMID 39272984, 2024). "In the same vein, JAK3 inhibition with 10 mg/kg decernotinib did not affect stroke-induced upregulation of Ccl2, Cxcl10, and Cxcl1, chemokines important for immune cell trafficking, nor proinflammatory mediators IL-1β, IL-6, Tnfα, Ptgs2, and Mmp-9 that exacerbate stroke damage." (PMID 28790974, 2017). "However, the expression of CCL2, CCL3, CCL4, CCL7, and CXCL2 was strongly increased after stroke, whereas CCL19, CCL20, and CXCL5 expression levels were not changed." (PMID 26640428, 2015).
Stroke (continued). "Although the expression of several studied chemotactic inflammatory mediators (chemokines CCL2, CCL3, CCL5, and CXCL2) was significantly increased in the early stage of this stroke model, there was no clear correlation between this expression and intensity of neurodegeneration (data not shown)." (PMID 24324296, 2013). "They showed upregulation of CCL5 but not CCL2, CCL3, and CCL4 on day 0 in stroke patients." (PMID 24324296, 2013). "Furthermore, we found CCR2 but not CCL2 to correlate with time to blood sample, SSS, and mRS, suggesting that CCR2 may be a potential biomarker for stroke severity and functional outcome." (PMID 33918875, 2021).
prostate carcinoma (218 papers, 2008 to 2026). A carcinoma that arises from epithelial cells of the prostate gland. "Revisiting the secretome analysis, CCL2, a chemokine implicated in cervical cancer, prostate cancer, and PDAC PNI, was identified as a potential player in guiding PDAC cells towards SCs; therefore, CCL2 was inhibited in CM via neutralizing antibody." (PMID 40160208, 2025). "It was determined that elevated serum levels of IL-8, TNF-α, and CCL2 are associated with accelerated progression to castration-resistant disease and correlate with poorer overall survival in prostate cancer patients." (PMID 39355131, 2024). "Meanwhile, IL‐8 secreted by PTEN‐deficient prostate cancer cells can also augment CAF‐derived CCL2 and CXCL12, leading to increased proliferation and migration of the cancer cells." (PMID 36608258, 2023). "Previous research has shown that an upregulation of the ratio of CCL2 to it receptor (CCL2/CCR2) in another hormonally-responsive cancer - prostate cancer - was associated with advancement of disease, metastasis and relapse." (PMID 37181043, 2023). "Abundant production of CCL2 caused the growth of prostate cancer, augmented the aggregation of macrophages in vivo, and induced neovascularization in colorectal cancer." (PMID 35408440, 2022). "In PC-3M prostate cancer cells, CCL2 was found to indirectly cause angiogenesis by upregulating VEGF expression in tumor cells." (PMID 36077785, 2022). "We identified HOXB13 as an upstream regulator of HOXA11-AS, and found that HOXA11-AS regulated the CCL2/CCR2 signaling associated with prostate cancer bone metastasis." (PMID 33514011, 2021). "This study identified that elevated serum levels of inflammatory cytokines IL-8, TNF-α, and CCL2 were associated with accelerated progression to castration resistant disease and correlated with poor overall survival in prostate cancer patients." (PMID 33076397, 2020). "Bone metastasis in prostate cancer is closely related to osteoblasts because prostate cancer cells secrete parathyroid hormone related proteins (PTHrP) that cause an increase in CCL2 expression in osteoblasts." (PMID 33182504, 2020). "In prostate cancer, CCL2 has been implicated as one of the main cytokines involved in tumor cell re-establishment in the bone marrow." (PMID 32585812, 2020). "Elevated serum levels of IL-6, IL-8, TNF-α, and CCL2 are associated with accelerated progression and poor prognosis in prostate cancer patients." (PMID 33076397, 2020). "CCL2 was recently found to be a diagnostic, predictive, and prognostic biomarker of prostate cancer and has been reported to be the most important chemokine for monocyte recruitment to prostate tumors." (PMID 30705401, 2019). "Enzyme-linked immunosorbent assay (ELISA) confirmed that CCL2 secretion was dramatically increased when prostate cancer cells and U937 cells were co-cultured." (PMID 28039457, 2017). "CCL2 is secreted by prostate cancer cells and tumor-associated macrophages (TAM) during coculture conditions that mimic ADT and induces prostate cancer cell migration/invasion via CCL2-dependent STAT3 activation and the EMT pathways." (PMID 26701731, 2016). "It remains to be determined if changes in CCL2 levels as well as any association of this change with the PSA level will be detected in patients with prostate cancer before or after receiving such therapy." (PMID 26701731, 2016). "Next, we analyzed the levels of markers that are often associated with enhancing cellular migration in CCL2-treated prostate cancer cells." (PMID 26701731, 2016). "Prostate cancer cells that express CCL2 have been shown to cause monocyte and osteoclast recruitment with resulting cancer cell growth and survival." (PMID 26317041, 2015). "CCL2 was measured at very low levels (<10 pg/mL) by enzyme-linked immunosorbent assays (ELISA) in prostate cancer cell supernatants and U-937 supernatants (147.5 ± 24 pg/mL)." (PMID 26317041, 2015).
prostate carcinoma (continued). "In this study, co-cultures of prostate cancer cells and monocytes showed greatly increased CCL2 levels associated with increased prostate cancer cell invasion." (PMID 26317041, 2015). "Recombinant human CCL2 protein added to the lower well of the Transwell apparatus caused dose-dependent stimulation of PC-3 prostate cancer cell invasion." (PMID 26317041, 2015). "Chronic inflammation is associated with CXCL12, CCL5, and CCL2, which are highly overexpressed in prostate cancer." (PMID 23362217, 2013). "For example, prostate cancer-associated fibroblasts promote immunosuppression on T cells by the release of transforming growth factor-β60 or by recruiting suppressive myeloid cells through the CCL2 and CXCL12 pathways." (PMID 39633050, 2025). "Given that RON signaling in prostate cancer cells promotes CCL2 production, which recruits tumor-associated macrophages, the secretion of GAS6 by tumor-associated macrophages to then promote RON activation adds an additional layer of cellular crosstalk to sustain RON signaling within the TME." (PMID 36833444, 2023). "Transcription factor homeobox B13 (HOXB13) was identified as an upstream regulator of HOXA11-AS.HOXA11-AS regulated bone metastasis-associated C-C motif chemokine ligand 2 (CCL2)/C-C chemokine receptor type 2 (CCR2) signaling in both PC3 prostate cancer cells and SaOS2 osteoblastic cells." (PMID 33514011, 2021). "Similarly, the regulation of CCL2 by STAT3 was also reported in prostate cancer cells and cancer-associated fibroblasts." (PMID 31781676, 2019). "In summary, prostatic epithelial AR silencing via siAR promotes STAT3 activation and EMT in prostate cancer cells via CCL2 induction, which may be associated with a secretory phenotype and pro-invasive characteristics of prostate cancer cells." (PMID 30871130, 2019). "Thus, we explored the effect of DT on the secretion of IL-8 or CCL2 from prostate cancer cells and macrophages using an enzyme-linked immunosorbent assay (ELISA) to confirm the data from the cytokine array." (PMID 28157698, 2017). "This study explored the role of CCL2 and NF-κB activity and indicates that these factors may be key molecular targets to inhibit inflammation-associated prostate cancer progression." (PMID 26317041, 2015). "Therefore, the initial objective of this study was to establish the existence of interplay between tumor-derived CXCL8 from PTEN-deficient prostate cancer cells and the potentiation of stromal-derived CCL2 and CXCL12 expression and/or signaling." (PMID 24970800, 2014). "Additionally, we observed increased Ccl2/7/11-Ccr2 interactions between fibroblasts and M2/TAMs upon Pten loss, suggesting that fibroblasts in prostate cancer may also play an active role in macrophage recruitment." (PMID 36511483, 2022). "Interestingly, this result is consistent with a recent pilot study of potential biomarkers for prostate cancer showing that CCL2 alone may serve as a diagnostic serum biomarker among six chemokines." (PMID 26701731, 2016). "In a mouse experimental model of prostate cancer, n-3 FAs lowered the infiltration of macrophages and CCL-2 expression." (PMID 40076892, 2025). "In another study, inhibition of ENO1 by HuL227 halted inflammation-induced migration of PC-3 prostate cancer cells and reduced CCL2 or TGFβ-enhanced migration of PC-3 and DU145 prostate cancer cells." (PMID 40214422, 2025). "In prostate cancer, it was shown that the expression of CCR2 in a prostate cancer cell line correlated with cell migration towards dorsal root ganglion that expressed CCL2." (PMID 39199567, 2024). "In terms of circulating levels of CCL2, it has previously been suggested that circulating CCL2 level in the blood is increased in prostate cancer and is a predictor of prostate cancer progression." (PMID 39199567, 2024).
prostate carcinoma (continued). "Another study including a patient cohort of 41 prostate cancers previously reported CCL2 tissue expression in ~50% of cases, with patient outcome significantly worse with lower survival time in patients with CCL2 overexpressing tumours." (PMID 39199567, 2024). "CCL2 is a TAMs attractant, and currently anti-CCL2 neutralizing antibodies in mouse xenograft models prevent prostate cancer metastasis." (PMID 39063032, 2024). "We then investigated if there was a difference in CCL2 concentration between prostate cancer ISUP grades." (PMID 39199567, 2024). "Preclinical studies have demonstrated that androgen deprivation induces the upregulation of CCL2 expression in prostate cancer cells, fostering tumour growth and metastasis through the recruitment of tumour-associated macrophages (TAMs)." (PMID 39199567, 2024). "In contrast, other studies have suggested a prognostic value for CCR2 and CCL2 with prostate cancer progression." (PMID 39199567, 2024). "In this present study, we confirmed that circulating CCL2 concentration was significantly higher in patients with prostate cancer compared with BPH and normal controls." (PMID 39199567, 2024). "Natsagdorj and his coworkers observed in vitro that cabazitaxel-resistant cell lines express high levels of CCL2, which induce invasion, migration, and chemoresistance in prostate cancer cells." (PMID 39003454, 2024). "Upregulation of CCL2/CCR2 and various immune conditions in prostate cancer are associated with cancer progression, metastasis, and relapse." (PMID 38468260, 2024). "The circulating level of CCL2 in the serum of prostate cancer patients at the time of diagnosis (n = 220) was measured by ELISA." (PMID 39199567, 2024). "An alternative strategy is to target the recruitment of macrophages by tumor cells through inhibiting the CCL2-CCR2 axis with CCL2-neutralizing antibodies which is currently being tested in metastatic castrate-resistant prostate cancer (NCT00992186)." (PMID 38638445, 2024). "Genetically engineered MSCs with CCL2 knockout can enhance the anti-tumor effect in an immune-competent syngeneic mouse model of prostate cancer." (PMID 36672395, 2023). "Although further studies are needed to evaluate the antitumor efficiency of CCL2/CCR2 axis blockade in GBM patients, it is worth noting that CCL2 neutralizing antibody (e.g., carlumab) shows a modest effect in patients with prostate cancer." (PMID 36594466, 2023). "We confirmed that tumor cell-derived CCL2 was crucial in regulating the migration activities of MSCs and in tumor growth using a syngeneic mouse prostate cancer model." (PMID 36672395, 2023). "Both CCL5 and CCL2 have been shown to enhance the migratory abilities of prostate cancer cells ultimately contributing to their migration to other parts of the body including to the bone, the most common site of prostate cancer metastasis." (PMID 36836690, 2023). "Although several chemokines are capable of recruiting TAMs to the TME, the chemoattractant C-C motif ligand 2 (CCL2), alias MCP1, is the key factor and is known to be induced in prostate cancer in response to AR inhibition." (PMID 36672395, 2023). "We found that CCL2 KO MSCs showed anti-tumor function when injected with murine prostate cancer cells into mice." (PMID 36672395, 2023). "Co-incubation of mouse prostate cancer cells with T. vaginalis made adipocytes to increase production of IL-4, CCL2, and IL-6, as well as mRNA levels of CCL2, IL-4, and IL-13." (PMID 37125086, 2023). "Prostate cancer patients present high expression of CCL2 in the tumor, and elevated levels of anti-CCL2 neutralizing autoantibodies." (PMID 37251376, 2023). "For example, increased secretion of CCL2 and IL‐8 from CAFs in advanced prostate cancer promotes cancer cell migration." (PMID 36608258, 2023). "Our results confirmed that tumor cell-derived CCL2 plays an essential role in the syngeneic prostate cancer model, possibly due to the recruitment of many immunosuppressive cells (e.g., TAMs)." (PMID 36672395, 2023).